WRAP53 (WD repeat containing antisense to TP53)
Description:
RNA chaperone that plays a key role in telomere maintenance and RNA localization to Cajal bodies. Specifically recognizes and binds the Cajal body box (CAB box) present in both small Cajal body RNAs (scaRNAs) and telomerase RNA template component (TERC). Essential component of the telomerase holoenzyme complex, a ribonucleoprotein complex essential for the replication of chromosome termini that elongates telomeres in most eukaryotes. In the telomerase holoenzyme complex, required to stimulate the catalytic activity of the complex. Acts by specifically binding the CAB box of the TERC RNA and controlling the folding of the CR4/CR5 region of the TERC RNA, a critical step for telomerase activity. In addition, also controls telomerase holoenzyme complex localization to Cajal body. During S phase, required for delivery of TERC to telomeres during S phase and for telomerase activity. In addition to its role in telomere maintenance, also required for Cajal body formation, probably by mediating localization of scaRNAs to Cajal bodies. Also plays a role in DNA repair: phosphorylated by ATM in response to DNA damage and relocalizes to sites of DNA double-strand breaks to promote the repair of DNA double-strand breaks. Acts by recruiting the ubiquitin ligase RNF8 to DNA breaks and promote both homologous recombination (HR) and non-homologous end joining (NHEJ).
Synonyms: TCAB1; WDR79; FLJ10385; DKCB3
Tractability: PROTAC: ubiquitination databases record sites on it.
Target class: Reader; Epigenetic regulator; Methyl-lysine/arginine binding protein; WDR domain
Gene: Protein-coding gene on chromosome 17 (7,686,071 to 7,703,505, forward strand). Ensembl gene ENSG00000141499.
Subcellular location: Nucleus, Cajal body; Chromosome, telomere; Chromosome
Subcellular location (Human Protein Atlas): Nuclear bodies; Cytosol; Nucleoplasm
Pathways (Reactome):
Cell Cycle: Telomere Extension By Telomerase
Metabolism of proteins: Association of TriC/CCT with target proteins during biosynthesis
Gene Ontology:
Molecular function: histone binding; identical protein binding; protein binding; protein carrier chaperone; protein-containing complex binding; protein-folding chaperone binding; RNA binding; RNA folding chaperone; telomerase RNA binding; ubiquitin protein ligase binding
Biological process: Cajal body organization; positive regulation of DNA repair; positive regulation of double-strand break repair; positive regulation of double-strand break repair via homologous recombination; positive regulation of double-strand break repair via nonhomologous end joining; positive regulation of establishment of protein localization to telomere; positive regulation of telomere maintenance via telomerase; protein localization to Cajal body; RNA folding; scaRNA localization to Cajal body; telomerase RNA localization to Cajal body; telomere formation via telomerase; telomere maintenance via telomerase
Cellular component: Cajal body; chromosome; cytosol; nuclear body; site of double-strand break; telomerase holoenzyme complex; nucleoplasm; chromosome, telomeric region
Genetic constraint (gnomAD): Loss-of-function variants: 29 observed, 61.31 expected, observed/expected ratio (o/e) 0.47, 90% interval 0.35 to 0.64. The upper end of that interval is the gene's LOEUF score, 0.64, which puts it in group 2 of 6, group 1 being the genes least tolerant of losing a copy. Missense variants: 667 observed, 751.44 expected, observed/expected ratio (o/e) 0.89, 90% interval 0.83 to 0.95. Synonymous variants: 281 observed, 299.63 expected, observed/expected ratio (o/e) 0.94, 90% interval 0.85 to 1.03.
Gene-disease validity (ClinGen):
ClinGen rates the evidence that WRAP53 causes each of these diseases.
dyskeratosis congenita (autosomal recessive): Moderate. Dyskeratosis congenita (DC) is a rare ectodermal dysplasia that often presents with the classic triad of nail dysplasia, skin pigmentary changes, and oral leukoplakia associated with a high risk of bone marrow failure (BMF) and cancer.
dyskeratosis congenita, autosomal recessive 3 (autosomal recessive): Moderate.
telomere syndrome (semidominant): Moderate. Accelerated aging syndromes often caused by inheritable gene mutations resulting in decreased telomere lengths.
Homologues: Orthologues: chimpanzee WRAP53 (99% identical), macaque WRAP53 (97% identical), pig WRAP53 (85% identical), guinea pig WRAP53 (80% identical), rabbit WRAP53 (79% identical), dog WRAP53 (78% identical), mouse Wrap53 (77% identical), rat Efnb3 (73% identical), tropical clawed frog wrap53 (47% identical), zebrafish wrap53 (46% identical), Drosophila melanogaster WDR79 (32% identical), Caenorhabditis elegans tcab-1 (20% identical).
Diseases named in the same sentence as WRAP53 in open-access papers:
WRAP53 is named in the same sentence as 43 diseases in open-access papers, as found by Europe PMC text mining. Sharing a sentence is not in itself a finding about the gene and the disease. The quoted sentences say what the papers report.
dyskeratosis congenita (12 papers, 2014 to 2023). "The importance of WRAP53 for telomerase-mediated telomere maintenance is underscored by the fact that mutations in the WRAP53 gene cause the two related telomeropathies, dyskeratosis congenita and Hoyeraal–Hreidarsson syndrome." (PMID 34026839, 2021). "Moreover, inherited mutations in the WRAP53 gene, resulting in impaired function of WRAP53, cause the cancer predisposition disorder dyskeratosis congenita." (PMID 26460974, 2015). "Autosomal-recessive variants in WRAP53 have been reported as disease cause in two unrelated patients with the classical phenotype of Dyskeratosis congenita (DC) (MIM 613988), supported by functional studies of the detected variants." (PMID 30552426, 2019). "Another genetic disease, known as dyskeratosis congenita (DKC), occurs due to mutations in a couple of genes encoding proteins that localize to CBs (e.g., EST1A, NHP2, NOP10, and WRAP53), and resulting in defective ribosome biogenesis and telomere maintenance." (PMID 32764415, 2020).
head and neck cancer (8 papers, 2012 to 2023). A primary or metastatic malignant neoplasm affecting the head and neck. "A similar observation was reported in head and neck cancer, where loss of nuclear WRAP53 is associated with reduced survival and enhanced radioresistance in patients with head and neck cancer." (PMID 26460974, 2015). "Similarly, loss of nuclear WRAP53 associates with poor prognosis in head and neck cancer." (PMID 26460974, 2015). "Higher transcript levels of RADS1 and WRAP53 at diagnosis have been shown to be associated with poor prognosis in ALL and head and neck cancer, respectively." (PMID 37894336, 2023). "In the future, we will focus on the detail mechanism of the TCAB1/WRAP53-mediated function in head and neck cancers." (PMID 25070141, 2014). "In our study here, we focused on the function of TCAB1, the WRAP53 isoforms except α, in tumorigenesis and development of head and neck carcinomas, so we used the symbol TCAB1 here but WRAP53." (PMID 25070141, 2014). "In agreement with our study, high expression of WRAP53 was a marker for poor prognosis in head-neck cancer." (PMID 22805008, 2012). "WRAP53 expression has been connected to prognosis and radiotherapy in head-neck cancer." (PMID 22805008, 2012).
breast carcinoma (7 papers, 2014 to 2025). "For instance, low WRAP53 protein levels have been linked to poor outcomes in breast cancer and are associated with decreased effects of radiotherapy." (PMID 39886381, 2025). "We have shown that protein levels of WRAP53 and WRAP53 RNA expression are associated with prognosis in breast cancer and resistance to radiotherapy." (PMID 36975842, 2023). "Consistent with the low WRAP53 mutation frequency reported in the Cosmic database, somatic mutations were rare in the breast cancer cohort studied here." (PMID 26460974, 2015). "Notably, the key gene WRAP53 is also found in the Breast-AdenoCA-related regions, which is related to the increased risk of breast cancer." (PMID 37782656, 2023). "We have shown that immunohistochemical assessment of WRAP53 protein using C1‐antibody is prognostic in early‐stage breast cancer, as low nuclear levels were associated with a higher incidence of locally recurrent cancer and death from breast cancer." (PMID 36975842, 2023). "The aim of this study was to evaluate WRAP53 protein and RNA levels as prognostic and predictive markers in the SweBCG91RT trial, in which breast cancer patients were randomized for postoperative radiotherapy." (PMID 36975842, 2023). "In conclusion, low WRAP53 protein is prognostic for local recurrence and breast cancer‐related death." (PMID 36975842, 2023). "The WRAP53 protein was found to localize both in the nucleus and the cytoplasm of the breast carcinoma cells, separately or in combination." (PMID 26460974, 2015). "Here we show that the sub-cellular localization of the WRAP53 protein has a significant impact on breast cancer survival, and thus has a potential as a clinical marker in diagnostics and treatment." (PMID 26460974, 2015). "This study is the first to describe the sub-cellular localization of the WRAP53 protein in primary breast carcinomas and identify WRAP53 as a potential prognostic biomarker." (PMID 26460974, 2015). "Here, we have analyzed WRAP53 protein expression in breast carcinomas and show that the sub-cellular localization of the protein has an impact on the mortality of breast cancer patients." (PMID 26460974, 2015). "The aim of this study was to investigate the prognostic significance of WRAP53 protein expression in breast cancer." (PMID 26460974, 2015). "We show here that the prognostic value of this protein in breast cancer is dependent on its sub-cellular localization, where the presence of WRAP53 in the nucleus correlates to better patient outcome." (PMID 26460974, 2015). "Increased levels of nuclear WRAP53 protein have been detected in head and neck squamous cell carcinoma, ovarian epithelial cancer, rectal adenocarcinoma, esophageal squamous cell carcinoma, as well as in breast cancer." (PMID 36975842, 2023). "Sequencing of WRAP53 gene in the test set revealed that somatic mutations in the gene are not common events in breast cancer (data not shown)." (PMID 26460974, 2015). "Tumors with low WRAP53 protein levels had a higher subhazard ratio (SHR) for local recurrence [1.76 (95% CI 1.10–2.79)] and breast cancer‐related death [1.55 (1.02–2.38)]." (PMID 36975842, 2023). "Breast cancer patients with tumor cells lacking the expression of WRAP53 in the nucleus had a significantly poorer outcome compared to patients with tumor cells expressing this protein in the nuclei (HR = 1.95, 95%CI = 1.09–3.51, p = 0.025)." (PMID 26460974, 2015).
breast carcinoma (continued). "SNPs in WRAP53 are found to be overrepresented in women with breast cancer, especially in estrogen receptor–negative breast cancer." (PMID 24626331, 2014). "While the lack of nuclear WRAP53 protein could be an important prognostic and treatment‐predictive biomarker, its relation to radiotherapy resistance in breast cancer has yet to be investigated." (PMID 36975842, 2023). "Univariate survival analysis showed that breast cancer patients with negative nuclear staining of the WRAP53 protein had a statistically significantly increased mortality compared to patients with positive nuclear staining (HR = 1.95, 95%CI = 1.09–3.51, p = 0.025)." (PMID 26460974, 2015).
lung carcinoma (7 papers, 2016 to 2023). "The involvement of WRAP53 in disease progression is evident in lung cancer, but whether different targets of WRAP53 variants exert different biological functions still requires further investigation." (PMID 36706151, 2023). "Reduced expression of WRAP53 has been previously correlated to attenuated DNA damage response and poor survival in ovarian and lung cancers, and suggests similar line of dysregulation in MM." (PMID 34944968, 2021).
ovarian carcinoma (7 papers, 2012 to 2024). A malignant neoplasm originating from the surface ovarian epithelium. "Low levels, in contrast to high levels, of nuclear WRAP53 protein have been associated with impaired survival in both breast and ovarian cancer." (PMID 36975842, 2023). "Common variations in WRAP53 (alias WDR79) have been associated with an increased risk for developing breast and ovarian cancer." (PMID 22805008, 2012). "In ovarian cancer, low levels of both WRAP53 mRNA and WRAP53 nuclear staining correlated with reduced survival." (PMID 36975842, 2023). "Downregulation of WRAP53 in ovarian cancer was recently shown to correlate with defective DNA repair and poor clinical outcome (, in press)." (PMID 26460974, 2015). "Indeed, recent reports show that downregulation of WRAP53 in ovarian cancer leads to defective DNA repair and poor clinical outcome of the patients (, in press)." (PMID 26460974, 2015).
non-small cell lung carcinoma (5 papers, 2017 to 2024). A group of at least three distinct histological types of lung cancer, including non-small cell squamous cell carcinoma, adenocarcinoma, and large cell carcinoma. "Over-expression of Wrap53 has been associated with several types of tumors, including head and neck squamous cell carcinoma (HNSCC), development of esophageal squamous cell carcinoma (ESCC), or tumor progression in non-small cell lung cancer (NSCLC)." (PMID 36769304, 2023).
rectal cancer (5 papers, 2012 to 2025). A primary or metastatic malignant neoplasm that affects the rectum. "Conversely, in rectal cancer, high WRAP53 expression in primary tumors and metastases was associated with poor prognosis, except in patients receiving radiotherapy, where it correlated with improved survival." (PMID 39886381, 2025). "In rectal cancer, it has also been shown that the protein levels of WRAP53 were reduced by preoperative radiotherapy, suggesting that WRAP53 negativity is enriched by radiotherapy." (PMID 36975842, 2023). "Our previous study showed that tumor necrosis was related to advanced stage and worse survival in rectal cancer patients, and WRAP53 level was significantly increased in primary tumor compared to normal mucosa, which was associated with poor prognosis." (PMID 33123477, 2020). "This exposes WRAP53 as a potential “oncoprotein” in early development of rectal cancer, and a new biomarker for early diagnosis of rectal cancer." (PMID 22805008, 2012). "Frequency of WRAP53 protein expression was increased in primary rectal cancer compared to the normal mucosa (p < 0.05)." (PMID 22805008, 2012). "We examined expression of WRAP53 protein in rectal cancers and analyzed its relationship to the response to preoperative radiotherapy and patient survival." (PMID 22805008, 2012). "The WRAP53 protein was examined by immunohistochemistry in normal mucosa, primary tumors and lymph node metastases from 143 rectal cancer patients participated in a Swedish clinical trial of preoperative radiotherapy." (PMID 22805008, 2012). "We found that WRAP53 was increased from normal mucosa to primary rectal cancers." (PMID 22805008, 2012). "Indeed, in rectal cancers with radiotherapy, there was a relationship of positive WRAP53 with increased apoptosis and decreased survivin." (PMID 22805008, 2012). "Considering previous reports on oncogenic properties of WRAP53 overexpression of WRAP53 contributes to malignant transformation, the enhanced WRAP53 in rectal cancer may be a sign of its involvement in the conversion of normal mucosa into cancer." (PMID 22805008, 2012). "WRAP53 protein may be a potential “oncoprotein” in rectal cancer development, and involved in induction of apoptosis in response to radiotherapy." (PMID 22805008, 2012). "Immunohistochemistry was carried out in primary rectal cancers (n = 143), along with available distant (n = 118) and adjacent (n = 81) normal mucosa as well as metastasis in the lymph node (n = 49) to examine the expression and localization of the WRAP53 protein." (PMID 22805008, 2012). "Although we could not find a difference of miR-302a expression between rectal cancers and normal rectal samples in non-RT patients, the expression of miR-302a was significantly higher in rectal cancers with necrosis and strong WRAP53 expression." (PMID 33123477, 2020). "In this study, we examined WRAP53 protein in biopsies, and surgical specimens from distant normal mucosa, adjacent normal mucosa, primary tumor and lymph node metastasis from the patients participated in a Swedish rectal cancer clinical trial of preoperative radiotherapy (Uppsala, 1986-11-17, Dnr." (PMID 22805008, 2012).
esophageal squamous cell carcinoma (4 papers, 2014 to 2023). Esophageal squamous cell carcinoma (ESCC) is a type of esophageal carcinoma (EC) that can affect any part of the esophagus, but is usually located in the upper or middle third. "Recently, increased expression of WRAP53 was observed in esophageal squamous cell carcinoma tissue compared to adjacent non-neoplastic esophageal mucosa tissue." (PMID 26460974, 2015).
breast tumors (2 papers, 2015 to 2023). "Low WRAP53 RNA levels were associated with almost a three‐fold decreased effect of radiotherapy in relation to ipsilateral breast tumor recurrence [IBTR; SHR 0.87 (95% CI 0.44–1.72)] compared with high RNA levels [0.33 (0.19–0.55)], with a significant interaction (P = 0.024)." (PMID 36975842, 2023). "We have studied the levels of WRAP53, a DNA repair protein, in 965 breast tumors and correlated this with the prognosis and effect of radiotherapy treatment." (PMID 36975842, 2023). "A tissue microarray was constructed from primary breast tumors and immunostained by a polyclonal WRAP53 antibody to assess the protein expression pattern." (PMID 26460974, 2015). "In this study, we describe the sub-cellular localization of WRAP53 in breast tumors and show that the protein expression impacts clinical outcome, independent of other common prognostic markers." (PMID 26460974, 2015). "A substantial diversity in WRAP53 expression levels was observed across the breast tumor samples." (PMID 26460974, 2015).
esophageal cancer (2 papers, 2014 to 2023). A primary or metastatic malignant neoplasm involving the esophagus. "The association between WRAP53 protein expression and clinicopathological features of esophageal carcinomas was also analyzed." (PMID 24626331, 2014). "Relationship between WRAP53 expression and clinicopathological characteristics of esophageal carcinomas in patients." (PMID 24626331, 2014). "WRAP53 mRNA expression was upregulated in 37/45 (82.2%) of the esophageal carcinoma specimens." (PMID 24626331, 2014).